IL2 (interleukin 2)
Diseases named in the same sentence as IL2 in open-access papers (continued):
Sharing a sentence is not in itself a finding about the gene and the disease.
infection (continued). "Our results suggest a potential mechanism for the association of higher levels of IL-2 expression with susceptibility to MS, in which the IL-2 inhibits the ability of the macrophages to suppress an autoimmune T-cell response to infection with neurotropic viruses." (PMID 21364747, 2011). "Significant associations under additive models were observed between Il2 and infection by nematodes and tick infestation; the TC haplotype was associated with an increased chance of infection by nematodes but, in the longitudinal study, a decreased probability of tick infestation." (PMID 22039363, 2011). "The STH infection effect (combined light and chronic infection groups) was associated with greater production of GM-CSF (P = 0.02) and IL-2 (P = 0.004) and the chronic STH infection effect with greater levels of GM-CSF (P = 0.007), IL-2 (P = 0.03), IL-5 (P = 0.01), and IL-10 (P = 0.01)." (PMID 21666788, 2011). "This outbreak provided an opportunity to test the hypothesis that simultaneous measures of M. tuberculosis-specific IFN-γ and IL-2 secretion may improve identification of individuals with the highest risk of recent infection with M. tuberculosis." (PMID 20652022, 2010). "Also, the concentration of IL-2 was significantly higher at the peak of oocyst shedding (14 days of infection) (P<0.01) than that at days 7 and 21 of infection in Se-adequate or –deficient mice." (PMID 19247447, 2009). "Therefore, we speculate that pathogenic infection may activate NF-κB signaling and evoke inflammatory cytokines secretion, leading to IL-2 elevation in lungs." (PMID 38967887, 2024). "Low-dose IL2 therapy caused significantly increased expansion of natural killer (NK) cells which implicated potential augmentation of anti-infectious cellular immunity and possibly explained the lower incidence of treatment-associated severe infections in the patients." (PMID 38646383, 2024). "In these models, the additional knockout of the interleukin-2/7 common gamma chain within lymphopenic mice is essential for susceptibility to L. loa adult development in subcutaneous tissues and bolsters both B. malayi and O. ochengi adult infections within the peritoneal cavity." (PMID 37426014, 2023). "In contrast, module 3 (M3) segregated in a different cluster of cytokines that include low IL-1β, IL-2, IL-12, moderate IL-17, IL-21, and high IFNγ, GM-CSF that were associated with low levels of lymphocytes and low titers of total IgG and IgG1 in the acute phase of infection." (PMID 33815363, 2021). "Hence, it will be of further interest to determine, whether the heightened IL-2 signaling in T-bet deficient strains contributes to their failure to accumulate at day 8 of infection." (PMID 32991634, 2020). "In addition, in animals inoculated with P. brasiliensis alone and those coinfected, sustained production of Th1 cytokines (i.e., IL-2 and IL-5) in both phases of infection can also indicate a protective response associated with the resistance of infected hosts against disease progression." (PMID 31019973, 2019). "rATG is a more potent immunosuppressant and could induce a higher risk of infection than IL2-AR." (PMID 30902050, 2019). "Interestingly, low levels of T cell-associated cytokines such as IL-2 are found in infection." (PMID 26512687, 2015). "Although strong antibody responses are important for clearance of and protection against HBV infection, the Th1-cell and CTL response to HBV and the associated antiviral cytokines (IFN-γ, TNF-a, and IL-2) may play a key role in virus resolution during natural infection." (PMID 22970140, 2012). "Using this strategy, we successfully generated a recombinant IAV-ΔNS1 virus carrying the human interleukin 2 (IL-2) gene, inducing robust secretion of bioactive IL-2 upon infection." (PMID 42012179, 2026). "This study aimed to describe the cytokine responses (IL-2, IL-6, IL-10, TNF-α, IFN-γ) associated with each infection." (PMID 41547724, 2026).
infection (continued). "For instance, research using immunocompetent C57BL/6 and BALB/c mice demonstrated that the resolution of infection occurred on day 16, primarily mediated by the production of IL-17A and IL-2." (PMID 41156648, 2025). "Consistent with prior reports, nutritional intervention significantly improved short-term nutritional and immune indicators (PA, Hb, TLC, IgA, IgG, IgM) and reduced inflammatory cytokines (IL-2, IL-6, TNF-α), thereby lowering infection risk." (PMID 41306668, 2025). "Four of the patients with prior infection displayed an increase in the IL-2 response and 3 a decreased response." (PMID 41012178, 2025). "Rapid IL-2 production following T cell activation serves as a key marker for evaluating immune responses, particularly during infections such as SARS-CoV-2." (PMID 40242761, 2025). "The cellular response associated with infection control leads to the specific proliferation of CD4+ T lymphocytes, which mostly produce interferon-γ (IFN-γ), tumour necrosis factor (TNF) and interleukin-2 (IL-2)." (PMID 41272851, 2025). "Their findings, based on intracellular cytokine analysis, including IL-2, revealed that both T cell subsets retained long-term memory to the virus post-infection." (PMID 40242761, 2025). "After infection, the cells were maintained in culture with IL-2 for up to three weeks, during which time viral gene expression progressively declines as the cells revert to a resting state, and a population of latently infected (GFP-) cells emerges." (PMID 40198713, 2025). "Immunological results of the present study showed that the infection induced a highly significant rise in the levels of both IL-2 and IL-4 compared to normal uninfected control in both the intestinal and muscular phases." (PMID 40679976, 2025). "Gene expression of pro-inflammatory cytokines IL-1β, IL-2, IL-4, and IL-6, as well as IFNγ was significantly upregulated in nasal turbinates in response to infection with all VOCs, compared to mock-infected hamster tissues." (PMID 40295859, 2025). "IL-2 levels can indicate the presence of memory T cells, which are vital for quick and effective responses to future infections." (PMID 40242761, 2025). "Our data revealed that the levels of most inflammatory cytokines, such as IL-8, IL-1β, IL-4, IL-6, and IL-2, etc., persistently increased with time during CV-A10 infection." (PMID 41165313, 2025). "IL-2 can increase the cytotoxicity of macrophages and induce activated macrophage to be resistant to infection." (PMID 40337274, 2025). "Animals that met endpoint criteria and were euthanized following exposure to NiV-M had rapidly increasing levels of IL-1RA, IFN-γ, IL-15, and IL-2, similar to what was seen in animals with NiV-M infection following intermediate particle exposure." (PMID 41460894, 2025). "We showed that infection with rCDC-9 P45 led to reduced expression of pro-inflammatory cytokines IL-2 and significantly reduced expression of IL-12 compared to infection with rCDC-9 P11." (PMID 41060027, 2025). "Ovarian hormones profoundly influence immune factors within the endometrium, including TNF-α and IL2, which are critical for infection prevention, endometrial preparation for implantation or menstruation, and subsequent repair." (PMID 40028534, 2025). "For comparison, at T1 IFN-γ responses were 4.7-fold higher and IL-2 responses 2.7-fold higher after infection vs. vaccination." (PMID 41012178, 2025). "In the CsCP2-immunized group, IgG1/IgG2a levels gradually increased, and IL-2 and IL-4 expression significantly surpassed that of the control group at four weeks post-infection." (PMID 40248698, 2025). "Functionally, ELISpot assays showed comparable IFN-γ secretion in both YG and AG ferrets post-infection, whereas IL-2 secretion was significantly higher in AG ferrets at 6 dpi (p < 0.01)." (PMID 40794649, 2025).
infection (continued). "High-dose infection with all the strains elicited significant increases in GM-CSF, IL-1β, IL-2, IL-4, IL-5, IL-6, and IL-12p70 when compared with the PBS control." (PMID 40333117, 2025). "In the rCsCP2 immunized group, IL-2 and IL-4 levels rose from the second and fourth weeks post-infection, while IFN-γ levels decreased noticeably, and IL-10 expression remained unchanged compared to controls." (PMID 40248698, 2025). "In the rCsCP3 immunized group, IFN-γ, IL-2, and IL-10 were elevated from the first week post-infection (P < 0.01), with IL-4 levels increasing in the second week." (PMID 40248698, 2025). "Long-term IFN-γ responses after MPXV infection were 4.3 times higher (p < 0.01), and IL-2 responses were 2.9 times higher (p = 0.05) than after vaccination." (PMID 41012178, 2025). "Critical role of B cell-derived IL-2 in Th2 cell differentiation was demonstrated in a mouse infection model with Heligmosomoides polygyrus, a strictly enteric helminth parasite." (PMID 41000383, 2025). "Variations in IL-2 production can occur depending on the type of pathogen, the stage of infection, and the overall immune status of the host." (PMID 41194029, 2025). "The IL-2/IFNγ T-cell responses to FCoV1 RBD post-first vaccination were negative for HOK, but extremely high for HOL, most likely caused by active infection and vaccine stimulation." (PMID 41295545, 2025). "In the lymph nodes, we observed significant increases in the levels of IL-4, IL-6, TNF, and IFN-γ at 22 days after infection and increases in the levels of IL-2, IL-1, and IL-10 in infected mice at 35 days." (PMID 39899646, 2025). "We didnot observe any changes in IL-2, IL-4, or IL-10 levels resulting fromthe infection; however, ravuconazole-treated mice presented higherlevels of IL-4, and combination therapy significantly increased theIL-4 and IL-10 compared to untreated infected mice." (PMID 40488037, 2025). "When analyzing IFN-γ and IL-2 responses combinedly, positive responses after vaccination declined from 18 to 16 out of 27 and after infection from 7 to 6 out of 7, i.e., from 67 to 59% and from 100 to 86%, respectively." (PMID 41012178, 2025). "When expression of the common IL-2R gamma chain (utilized by IL-2, −4, −7, −9, −15, and −21), was analyzed, like gp130, it was ubiquitously expressed by all developmental stages, although infection did upregulate its expression." (PMID 39868131, 2025). "IL-2 and IL-22, cytokines involved in T-cell activation and mucosal immunity, have been proposed as potential biomarkers for infection subtype differentiation, though results remain inconclusive." (PMID 40647525, 2025). "B cell-intrinsic MHCII, IL-4Rα, and IL-2, as well as parasite-specific antibodies are all required for parasite clearance upon secondary infection." (PMID 41000383, 2025). "Infection of the strain B10.O20 resulted in 15-350× increase of splenocytes’ production of IFNγ IL-2, IL-4, IL-6, IL-10 and IL-17." (PMID 41164189, 2025). "Here, we demonstrate that BLIMP1 deficiency results in augmented IL-2 signaling in TFH, TFR, TEFF, and cTreg cells after infection with influenza virus, with the most robust effect in the Treg cells." (PMID 40680114, 2025). "Contrarily, both single-cell Jurkat–SMPU clones exhibited much less (#21) to non-existent (#29) background eGFP activity following activation with PHA-P/IL-2, thus identifying suitable candidate clones and appropriate mitogens for infection experiments." (PMID 39599568, 2024). "The proportion of multi-functional T cells decreased while monofunctional T cells (CD107a+/IFN-γ-/TNF-α-/IL-2-) gradually increased from day 60 after Cl-13 infection." (PMID 38547316, 2024). "In contrast, after restimulation with anti-CD3 and anti-CD28 mAbs, infection-induced mouse MLN cells secreted low levels of Th1 cell cytokines IL-2 and IFN-γ." (PMID 38166140, 2024).
infection (continued). "Instead, the percentage of CD8+ T cells producing IL-2 was higher after stimulation with IE-1, pp65, and gHgLpUL12L peptide pools in control subjects with remote infection than in pregnant women with HCMV primary infection at the early and late time points." (PMID 39336935, 2024). "These cells exhibited effector and central memory phenotypes, similar to natural infection and after vaccination, potentially sustained by IL-2 and TNF-α, crucial for memory T-cell proliferation and survival." (PMID 39763646, 2024). "Th1 cells activate macrophages by secreting factors such as IFN-γ and IL-2, enhancing their ability to combat M. tuberculosis and promoting the formation of granulomas to control the infection." (PMID 39763671, 2024). "Conversely, SmLE infection resulted in elevated levels of IL-2, IL-4, IL-5 and IL-6 and a decrease in IL-13 in C57BL/6 but not in BALB/c mice." (PMID 38711063, 2024). "Consistent with this, injection of IL-2/S4B6 complexes at days 3–5 post-infection substantially boosted the expansion of both OT-I WT and OT-I Srf−/− cells." (PMID 39261466, 2024). "IL-2 mediated CD8+ T cell proliferation during infection thus depends on the control of cytoskeletal dynamics and actin gene expression by MRTF-SRF signalling." (PMID 39261466, 2024). "The levels of pro-inflammatory cytokines such as IL-1α, IL-1β, IL-2, IL-6, IL-12, IL-17, INFγ, and TNFα increased in the serum of mice infected with fungal strains from a very early stage (3 h) to 7 days post infection." (PMID 38783167, 2024). "Mrtfab- or Srf-null splenic T cells were harvested 3 days post-infection, when proliferation of OT-I WT and OT-I Mrtfab−/− cells was comparable, and cultured for 72 h either alone, with IL-2, or with IL-12, which allows maintenance of IL-2Rα expression." (PMID 39261466, 2024). "Throughout the 21-day infection period, the levels of cytokines, such as IL-2, TNF-α, and IFN-γ were much lower in PD-1+TIM-3+ exhaustion-like CD8+ T cells than in PD-1+TIM-3-CD8+ T cells, which are recognized as activated cells." (PMID 39664572, 2024). "ICVB-1042 infection of A375-Luc2 cells led to a significant increase in IFNγ and IL-2 production by allogeneic PBMCs." (PMID 39271928, 2024). "Forty-eight hours after G. parasuis challenge, IL-1β, IL-10, IL-18, TNF-α and IFN-γ mRNA expression was increased, and IL-2 and IL-8 mRNA expression was decreased in the infection group compared to the control group (P < 0.001)." (PMID 39075562, 2024). "Based on the results, the mRNA levels as well as IL-1β, IL-6, IL-8, IL-10, IL-18, TNF-α and IFN-γ were significantly upregulated, and the IL-2 level was decreased in the infection group compared to the control group (p < 0.05)." (PMID 38582846, 2024). "Our cross-sectional study clearly demonstrated that SARS-CoV-2 specific IL-2-producing T cells are maintained up to 12 months after vaccination or infection, although antibody levels and IFN-γ-producing T cells decline over time in allogeneic HCT recipients." (PMID 38842630, 2024). "Pro-inflammatory cytokines such as TNF-α, IL-1β, IL-6, and IL-2 play several key roles in the brain, as follows: (i) They are crucial in initiating and regulating inflammation in response to infection, injury, or disease." (PMID 39337280, 2024). "For instance, cytokines like IL-2, necessary for T cell proliferation, are controlled at the translational level within SGs, which affects IL-2 production and the subsequent expansion of T cells in response to infection." (PMID 39684660, 2024). "This action reduces the transcription of pro-inflammatory cytokines such as interleukin-2 (IL-2), thereby mitigating the inflammatory response during infection." (PMID 39359246, 2024). "It activates T cells through co-stimulation in the early stage of the inflammatory response, leading to proinflammatory factor secretion (e.g., IL-2) and enhanced body’s ability to resist infection." (PMID 38603712, 2024).
infection (continued). "The expression of GM-CSF, IL-4, IL-5, IL-10, IL-13, KC, and VEGF in Th2 cells, and IL-2, IL-4, IL-5, IL-10, and IL-17 in NK cells significantly increased after infection (PBS-treated group)." (PMID 39264964, 2024). "In Lm-OVA/Cl-13 mice, however, OVA257-specific CD8+ Tm cells lost the capacity to produce IL-2 as early as day 40 post Cl-13 infection." (PMID 38547316, 2024). "More specifically, increased levels of IFN-γ establish a Th1-dominant microenvironment, inhibiting interleukin 2 (IL-2) activity, which plays an essential role in the priming of Th2 responses and the protection against this infection." (PMID 39728129, 2024). "IL-2 signaling is essential for the generation of Th1 cells specific to viral antigens in the lung following infection." (PMID 39519310, 2024). "Considering cell cultures after stimulation with 1 μg/mL per peptide, median IFN-γ responses were 4.7-fold higher and IL-2 responses 2.7-fold higher after infection vs. vaccination." (PMID 38400115, 2024). "During infection the response to IL-2, including STAT5 phosphorylation and proliferation, is facilitated by cell clustering and LFA-1/ICAM-1 interaction." (PMID 39261466, 2024). "But at the same time, we observed that immunization with ai-Nbs, especially aiChlNP-75 and -81, leads to an increase in IL-2 expression to the level seen during natural infection." (PMID 38396724, 2024). "In KO THP-1dM cells, Lt-P10 infection induced a significant increase of IL-10 (p = 0.02) and a significant reduction of IL-2 (p = 0.03); TGF-β production was only marginally modified." (PMID 38707903, 2024). "The percentage of CD4+ T cells producing IL-2 was higher after stimulation with pp65 peptide pool in control subjects with remote infection than in pregnant women with HCMV primary infection at the early and late time points." (PMID 39336935, 2024). "Humrich and his team noted that a range of adverse effects were noted among patients who received low-dose IL2 therapy and five severe life-threatening adverse effects/infections were seen during the follow-up period of the study." (PMID 38646383, 2024). "Here authors show that MRTF/SRF inactivation leads to decreased IL-2 mediated CD8 + T cell proliferation during infection, resulting from disrupted homotypic cell clustering and reduced retention of IL-2." (PMID 39261466, 2024). "But at the same time, we observe that immunization with the ai-Nbs, especially aiChlNP-75 and -81, induces almost the same level of IL-2 as natural infection." (PMID 38396724, 2024). "As reported in other studies, effector T-cells probably secrete IFN-γ, since it is the cellular subset actively fighting the infection, whereas IL-2 would be secreted by memory T-cells." (PMID 38212416, 2024). "Viable PBMCs from PWoH were infected with increasing copies of pseudo-HIV (labeled VsVG Luc) in the presence of IL-2 with an increase in the viral load, which was inhibited at the highest multiplicity of infection by the addition of raltegravir (RAL)." (PMID 39483879, 2024). "Cytokine release analysis showed significantly elevated IL-2 responses in all seropositive individuals and elevated IL-1β responses in those recovered from symptomatic infection." (PMID 37885896, 2023). "The infection-induced CD4 effectors required signals from autocrine IL-2 to effectively differentiate into long-lived CD4 memory." (PMID 38152398, 2023). "Th1‐like immune response involves cytokines such as IFN‐γ, IL‐2, and TNF‐α, which are associated with controlling the infection and mild to moderate disease in dogs." (PMID 38053473, 2023). "When PHA/IL-2-activated T cells were infected with the corresponding “bald” virus, none (or very few) cells containing type II NEIs were observed after 3 h of infection." (PMID 37563144, 2023). "The expression of IFNγ and IL-2 in PBMC co-cultured with KMeC infected with rNDV-cIFNγ was higher than in infection with rNDV-GFP." (PMID 37022566, 2023).